MIR122 (microRNA 122)
Synonyms: hsa-mir-122a; hsa-mir-122; miR-122; MIR122A; MIRN122; MIRN122A; miRNA122; miRNA122A
Gene: MicroRNA gene on chromosome 18 (58,451,074 to 58,451,158, forward strand). Ensembl gene ENSG00000284440.
Gene Ontology:
Biological process: miRNA-mediated post-transcriptional gene silencing
Cellular component: RISC complex
Homologues: Orthologues: chimpanzee ptr-mir-122 (99% identical), macaque mml-mir-122a (99% identical), dog MIR122 (98% identical), pig ssc-mir-122 (98% identical), rabbit MIR122 (93% identical), guinea pig MIR122 (75% identical), mouse Mir122 (75% identical), zebrafish mir122 (75% identical), tropical clawed frog xtr-mir-122 (74% identical).
Diseases named in the same sentence as MIR122 in open-access papers:
MIR122 is named in the same sentence as 7 diseases in open-access papers, as found by Europe PMC text mining. Sharing a sentence is not in itself a finding about the gene and the disease. The quoted sentences say what the papers report.
brain tumors (1 paper, 2018). "For example, it was reported earlier that MIR124 and 137, which are predominant in the brain, are frequently downregulated in brain tumors, such as GBM, and that downregulation of MIR122 induces HCC carcinogenesis." (PMID 29695138, 2018).
Hepatic steatosis (1 paper, 2024). Steatosis is a term used to denote lipid accumulation within hepatocytes. "On the other hand, other studies found that MIR122 levels are significantly lower in NASH patients in Western populations and that MIR122 expression decreases significantly with the progression of hepatic steatosis." (PMID 39618816, 2024).
cancer (2 papers, 2015 to 2024). A tumor composed of atypical neoplastic, often pleomorphic cells that invade other tissues. "The involvement of MIR122 has been reported to be a tumor suppressor in inflammation, fibrosis, cancer cell proliferation, invasion, metastasis, and apoptosis." (PMID 39618816, 2024).
MIR122 also shares sentences with these, for which no sentence is quoted: hepatocellular carcinoma (2 papers); tumor (2); biliary atresia (1); infection (1).